IFITM3 (interferon induced transmembrane protein 3)
Diseases named in the same sentence as IFITM3 in open-access papers (continued):
Sharing a sentence is not in itself a finding about the gene and the disease.
COVID-19 (continued). "This study aimed to investigate whether IFITM3 rs6598045, quantitative polymerase chain reaction (qPCR) cycle threshold (Ct) values, and severe acute respiratory syndrome coronavirus 2 (SARS-CoV-2) variants are associated with an increased mortality rate of COVID-19." (PMID 36403064, 2022). "mRNA levels of ADAM17, IFITM3, IL6, CXCL10, CXCL11, IFNG and TYK2 were increased in PBCs of COVID-19 patients (n = 73) compared with controls (n = 47), independently of sex." (PMID 36009555, 2022). "Analyses in the comparative COVID-19 cohort also suggest the possible participation of IFITM1 and IFITM3 in antiviral defenses against SARS-CoV-2." (PMID 35708622, 2022). "Similarly, other genes involved in type I interferon signaling (IFITM1 and IFITM3) and cellular activation (UBC, FOS, and DUSP1) were increased in a severity-dependent manner, suggesting an enhanced EF B-cell activity associated with an overt inflammatory condition in severe COVID-19." (PMID 35899045, 2022). "Thus, from our results it can be hypothesized that increased IFITM3 expression in blood cells can contribute to the lymphopenia that is commonly observed in patients with COVID-19, and which was suggested could serve as a predictor for the prognosis of patients." (PMID 36009555, 2022). "Taken together, our data suggest that, in women with severe COVID-19, IFITM1 and IFITM3 proteins participate in trophoblastic immune response and possibly promote placental protection against SARS-CoV-2." (PMID 34257394, 2021). "In addition, the expression of VANGL2 presented a reverse correlation with IFITM3, ISG15, GBP1, and TRIM27, which have been reported to play important roles in antiviral immunity in the COVID-19 patients’ database." (PMID 37352355, 2023). "Therefore, this study investigated the impact of the IFITM3 rs34481144 and clinical parameters on the likelihood of SARS-CoV-2 infection and COVID-19 mortality in Iranian patients." (PMID 37323564, 2023). "Finally, analyses in a comparative cohort also identify an induction of IFITM3 expression and correlation of IFITM1 with clinical variables in individuals with severe COVID-19, which deserve further investigation in more extensive studies." (PMID 35708622, 2022). "Hence, we analyzed the relative mRNA expression of IFITM1 and IFITM3 in our cohort of patients with severe influenza A(H1N1), using HC and individuals with severe COVID-19 as reference." (PMID 35708622, 2022). "Interestingly, the expression pattern of ADAM17, IFITM3 and IFNE in PBCs was related to both the severity of COVID-19 evolution and obesity status, especially in the male patients." (PMID 36009555, 2022). "Regarding COVID-19, our findings in COVID-19 critically ill patients showed the expression of IFITM3, but not IFITM1." (PMID 35708622, 2022). "In the NK cells and (to a lesser extent) non-classical monocytes of patients with COVID-19, we found remarkably high expression of interferon-induced transmembrane protein 3 (IFITM3)." (PMID 34424199, 2021). "Materials and Methods: Clinical exome data of 103 individuals was analyzed to identify sequence variants in five selected candidate genes: ACE2, TMPRSS2, CD209, IFITM3, and MUC5B to assess their prevalence and role to understand the COVID-19 infectivity and progression in our population." (PMID 33101356, 2020). "In the current study, any genotype associated with IL6 rs1800796, IL-10 rs1800896, TNF -α rs1800629, and IFITM3 rs12252 SNPs was significantly different between COVID-19 survivors with and without post-COVID pain, and, therefore, also with different pain phenotype features." (PMID 36233516, 2022). "Interestingly, IFITM1 and IFITM3 expression levels were not correlated with most clinical characteristics and comorbidities of COVID-19 patients and did not influence in-hospital complications or mortality." (PMID 35708622, 2022).
COVID-19 (continued). "Again, like results for ADAM17, a correlation between BMI and IFITM3 gene expression in PBCs was found in the COVID-19 patients, but not in the controls, and it was stronger and of higher statistical significance when only the male patients were considered in the linear regression model." (PMID 36009555, 2022). "In module 2, enhanced expression of glycolysis (GAPDH and TPI1) and IFN response (IFITM2, IFITM1, IFITM3, IFNGR2, and ISG20) genes in human COVID-19 patients, particularly severely ill patients, may promote the differentiation of unswitched memory B cells into plasmablasts." (PMID 33936072, 2021). "Based on that, we can suggest that severe COVID-19 cases might be due to either non-functional IFITM3 by SNP, failure of lung cells to upregulate IFITM3 in response to interferon, a mutation in amphipathic helix sequence or modification in S-palmitoylation." (PMID 32595654, 2020). "Interestingly, linear regression analyses showed IFITM3 to be upregulated in human BALF MΦ from patients affected either by moderate or severe COVID-19 (data not shown), which may well reflect anti-viral type I IFN response." (PMID 38034686, 2023). "In fact, an ROC analysis showed that IFITM1, but not IFITM3, distinguishes severe pandemic influenza A(H1N1) from COVID-19." (PMID 35708622, 2022). "In contrast, IFITM3 is overexpressed in both pandemic influenza A(H1N1) and COVID-19 and did not correlate with differences in survival." (PMID 35708622, 2022). "With non-severe (non-ICU) COVID-19, there was increased expression of the viral entry gene (CTSL (p < 0.05)) and increased antiviral response genes (MX1 (p < 0.0001), SAMHD1 (p < 0.0001), TRIM25 (p < 0.01), IFITM3 (ns))." (PMID 33633121, 2021). "For patients with COVID-19 who were not admitted to ICU, there was a statistically significant relationship between viral defense genes and CTSL expression, the four predictors (MX1, TRIM25 SAMHD1 and IFITM3) accounted for 65.56% of the variance (adjusted R2 = 0.656, p-value = 8.796–11)." (PMID 33633121, 2021).
glioma (19 papers, 2013 to 2025). A benign or malignant brain and spinal cord tumor that arises from glial cells (astrocytes, oligodendrocytes, ependymal cells). "Considering these evidences that IFITM proteins are critical for cell stemness and angiogenesis, we attempted to explore the role of IFITM3 in GSCs and glioma angiogenesis and understand the potentially underlying mechanism." (PMID 38218875, 2024). "Therefore, the mouse glioma cell line GL261 was transduced with a lentivirus encoding for IFITM3-IRES-tdTomato or a control lentivirus encoding for dsRed-IRES-tdTomato." (PMID 27835870, 2016). "However, the precise function and underlying mechanism of IFITM3 in glioma pathogenesis remain unclear." (PMID 24370119, 2013). "Taken together, these data indicated that IFITM3 expression was elevated in glioma samples, especially in GBM sample." (PMID 38218875, 2024). "IHC staining of glioma samples indicated a positive relation between IFITM3 expression and tumor grade." (PMID 38218875, 2024). "To examine the expression of IFITM3 in GBM, we investigated IFITM3 gene expression level in glioma datasets from The Cancer Genome Atlas (TCGA) and Chinese Glioma Genome Atlas (CGGA)." (PMID 38218875, 2024). "To clarify the role and molecular mechanism of IFITM3 in Glioblastoma multiforme (GBM) progression, we investigated the expression of IFITM3 in glioma datasets culled from The Cancer Genome Atlas (TCGA) and Chinese Glioma Genome Atlas (CGGA)." (PMID 38218875, 2024). "IFITM1 and IFITM3 expression correlates with poorly differentiated gastric, colon and glioma tumor tissues." (PMID 36466909, 2022). "In KIRC and glioma, high expression of IFITM3 was related to a better prognosis, while in SKCM, IFITM3 was a risk prognostic factor." (PMID 34456915, 2021). "Ifitm3 was highly expressed by the Mo/MΦ population, but appeared in a substantial fraction of MG, showing its low specificity in Mo/MΦ within glioma TME." (PMID 33608526, 2021). "Regarding the prognostic value of IFITM3, high expression of IFITM3 was associated with better prognosis in KIRC and glioma, while in SKCM, IFITM3 was a risk prognostic factor." (PMID 34456915, 2021). "Early work suggested IFITM3 is a cancer biomarker, following observed overexpression in colonic cancers and gliomas." (PMID 33364194, 2020). "IFITM3 is not only an invasive gene in colon cancer but highly expressed in most cancers such as breast cancer, glioma, melanoma, gastric cancer, and cervical cancer." (PMID 31273201, 2019). "Many previous studies have demonstrated that IFITM3 is a tumor-promoting gene overexpressing in many malignancies, including gliomas, colorectal cancer, and breast cancers." (PMID 31273201, 2019). "Interferon induced transmembrane protein 3 (IFITM3) plays an important role in glioma cell growth and migration." (PMID 27344170, 2016). "In order to evaluate the effects of IFITM3 on glioma growth in vivo, rsBTPCs with an enhanced expression of IFITM3 were used in glioma xenografts." (PMID 27835870, 2016). "Previously, IFITM3 has been described to affect glioma cells; therefore, the role of IFITM3 in the formation and progression of brain tumors has been investigated in vivo." (PMID 27835870, 2016). "In recent studies, IFITM1 and IFITM3 were proposed as protumorigenic factors, as knock-down of these proteins inhibited proliferation, migration, invasion and colony formation of glioma cell lines." (PMID 27835870, 2016). "At this stage, data presented in this study argues against a significant role of IFITM3 in glioma formation, progression or radio-resistance." (PMID 27835870, 2016). "Our results were consistent with previous researches that demonstrated that IFITM3 is overexpressed in many hunman malignancies, such as gastric cancer, colorectal cancer, oral squamous cell carcinoma, glioma, and breast cancer." (PMID 26539332, 2015). "In this study, we showed the positive correlation between the expression levels of IFITM3 and pathological grades of glioma by IHC." (PMID 24370119, 2013).
glioma (continued). "To study the role of IFITM3 in glioma, we employed lentivirus-mediated short hairpin RNA (shRNA) to knock down IFITM3 in human glioma cell line U251." (PMID 24370119, 2013). "Following closely, we investigated the phenotype of IFITM3 knockdown on glioma cell growth and tumorigenesis in vitro using lentivirus-mediated loss-of-function strategy." (PMID 24370119, 2013). "A Recent finding indicated that TGFβ-regulated IFITM3 expression facilitates glioma cell invasion." (PMID 38218875, 2024). "The expression level of IFITM3 in astrocytoma cells is higher than in normal astrocytes, and the knockdown of IFITM3 by RNAi successfully inhibited cell proliferation and migration and promoted the apoptosis of glioma cells." (PMID 37602193, 2023). "In addition to carcinomas, which are the most commonly studied tumor types, gliomas, acute myeloid leukemia and B-lymphoid malignancies show IFITM3 overexpression." (PMID 36466909, 2022). "In addition, IFITM3 levels respond to the stimulation of TGF-β in glioma, and the knockdown of IFITM3 blocked TGF-β-mediated invasion of tumor cells by suppressing STAT3 phosphorylation." (PMID 34456915, 2021). "However, our data suggest that the presence of IFITM3 in the cells is necessary for RD-LPS-induced EPC activation, in agreement with a recent study pinpointing the possible role of IFITM3 in glioma cell growth and migration." (PMID 31665090, 2019). "Additionally, a syngeneic model based on the mouse glioma cell line GL261 was applied in order to consider the possibility that IFITM3 relies on an intact immune system to unfold its tumorigenic potential." (PMID 27835870, 2016). "Therefore, the role of IFITM3 in brain tumor initiation and progression has been investigated using various glioma models in vivo." (PMID 27835870, 2016). "The authors suggest that IFITM1, a homolog of IFITM3, may be produced by glioma cells so as to antagonize the attack by the host immune system by promoting cell proliferation and invasion." (PMID 27835870, 2016). "However, further experiments are needed to elucidate the mechanism of IFITM3 in glioma cell growth and migration." (PMID 24370119, 2013). "Our results provide new evidence for the involvement of IFITM3 in carcinogenesis, and suggest that RNAi-directed IFITM3 silencing may be a potent therapeutic tool in glioma." (PMID 24370119, 2013). "In our study, lentivirus-mediated RNAi was used to knock down IFITM3 in human glioma cells." (PMID 24370119, 2013). "We analyzed the expression of IFITM3 in human glioma specimens by immunohistochemistry and found the expression levels of IFITM3 were up-regulated in varying degrees and positively correlated with glioma of pathological grade I ~ II and III ~ IV (P < 0.05)." (PMID 24370119, 2013). "In our study, we found IFITM3 knockdown significantly reduced the migration capacity of U251 cells, indicating that IFITM3 might play an essential role in glioma metastasis." (PMID 24370119, 2013). "Our findings provide new evidence that IFITM3 plays an important role in glioma cell growth and migration, suggesting that silencing of IFITM3 by RNA interference (RNAi) may be a potential approach to suppress glioma growth." (PMID 24370119, 2013). "Thus, this study confirms a crucial role of IFITM3 in glioma tumorigenesis, suggesting IFITM3 as an oncogene in human glioma." (PMID 24370119, 2013). "However, further investigation regarding molecular mechanism, by which IFITM3 influences glioma progression remains unclear." (PMID 38218875, 2024). "For example, in gastric cancer, knockdown of IFITM3 significantly inhibited the migration, invasion, and proliferation of tumor cells in vitro, and similar results were observed in oral squamous cell carcinoma, colorectal cancer, breast cancer, glioma, and other tumors." (PMID 38239300, 2024). "Together, IFITM3 may promote human glioma growth by inducing cell cycle arrest and apoptosis." (PMID 24370119, 2013).
glioma (continued). "Results showed a markedly elevated expression of IFITM3 in GBM, compared to lower grade gliomas (grade II, III)." (PMID 38218875, 2024). "We examined IHC staining with IFITM3 from human protein atlas (HPA) and observed a strong intensity in high grade glioma, while a weak intensity was documented in low-grade glioma." (PMID 38218875, 2024). "Knocking down IFITM3 reduces TGF-β and leads to STAT3 phosphorylation, which is crucial for glioma development." (PMID 33364194, 2020). "However, the precise role of IFITM3 in glioma pathogenesis remains unknown." (PMID 24370119, 2013). "The present study demonstrates that IFITM3 is preferentially expressed in GSCs and decreased markedly in differentiated glioma cells, yet has no significant impact on GSC self-renewal ability." (PMID 38218875, 2024). "As of yet, a reduction of the proliferation in conventional glioma cell lines as a consequence of IFITM3 knock-down has not been confirmed in BTPCs." (PMID 27835870, 2016). "In brief, 20,000 1080 cells transduced with IFITM3-myc or GFP control were exposed to increasing doses of γ-radiation ranging from 10 Gy to 60 Gy, which is the highest dose of IR used during treatment of human gliomas." (PMID 27835870, 2016). "These experiments, however, were conducted only in vitro and the role of IFITM3 in the glioma formation and progression has not been addressed in a mouse tumor model, which this study sought to resolve." (PMID 27835870, 2016). "GL261 cells ectopically expressing IFITM3 were implanted into the striatum of immunocompetent mice without influencing the survival of glioma-bearing animals." (PMID 27835870, 2016). "Interestingly, low oxygen level induced increased IFITM3 and HIF1α expression in GSCs, rather than glioma cell lines." (PMID 38218875, 2024). "Nevertheless, the role of IFITM3 in glioma formation in vivo has not been investigated, yet." (PMID 27835870, 2016). "Moreover, according to another database, namely REMBRANDT, there is very low variation in IFITM3 expression in glioma samples (data not shown)." (PMID 27835870, 2016). "Thus, the ectopic expression of IFITM3 did not affect angiogenesis or MG recruitment in the immune competent environment of the GL261 glioma model." (PMID 27835870, 2016).
Alzheimer disease (18 papers, 2020 to 2025). A progressive, neurodegenerative disease characterized by loss of function and death of nerve cells in several areas of the brain leading to loss of cognitive function such as memory and language. "In mice, IFITM3 KO reduced amyloid plaque formation, while enhanced association between IFITM3 and ɣ-secretase complexes were noted in patients with late onset Alzheimer's disease." (PMID 36435199, 2023). "Ifitm3 was identified as an innate immunity protein that predominantly associated with Alzheimer’s disease and cancers." (PMID 35802304, 2022). "IFITM3 has recently been identified as a modulator of γ-secretase activity that is associated with aging and Alzheimer's disease." (PMID 33329316, 2020). "Notably, tau and beta amyloid have been shown to stimulate microglia and upregulate IFN-I via cGAS-STING, a pathway that is furthermore linked to IFITM3 further linking innate immunity and Alzheimer’s disease." (PMID 38562226, 2024). "IFITM3 is another notable junction where innate immunity encounters neuroinflammation and Alzheimer’s disease mechanisms." (PMID 38785545, 2024). "In some study about neurodegeneration, such as Alzheimer’s disease, investigators have found that IFITM3 can act as γ-secretase modulatory protein and increase the deposition of amyloid-beta in brain via inflammatory mechanisms." (PMID 36994418, 2023). "IFITM3 expression is upregulated in astrocytes and microglia in the brains of the 5xFAD Alzheimer’s disease mouse model, and IFITM3 mRNA and IFITM3 protein are expressed in neurons." (PMID 36325336, 2022). "Notably, IFITM3 expression rises with age and is observed in mouse models harboring familial Alzheimer’s disease genes, suggesting a link of IFITM3 levels to Alzheimer’s disease susceptibility." (PMID 41197719, 2025). "There is evidence that the enzymatic activity of γ-secretase can also be influenced by interferon-induced transmembrane protein 3 (IFITM3), which is upregulated in tissue samples from certain late-onset Alzheimer’s disease patients and exhibits a positive correlation with γ-secretase activity." (PMID 40927393, 2025). "Moreover, for the first time, our study shows a regulatory relationship between Bin1 and Ifitm3, two Alzheimer’s disease-related genes in microglia." (PMID 35526014, 2022). "In Alzheimer's disease, inflammatory cytokines induce IFITM3 expression in neurons and astrocytes; IFTM3 then binds to γ-secretase to upregulate activity, increasing the production of amyloid-β (the main component of the amyloid plaques found in Alzheimer's disease patients)." (PMID 36414996, 2022). "In Alzheimer’s disease (AD), IFN-induced transmembrane protein 3 (IFITM3) expressed in neurons and astrocytes regulates amyloid-β (Aβ) production and aggregation, aggravating neuroinflammation and neuronal loss." (PMID 41359111, 2025). "In our model, we examined whether type I interferon signaling dysregulation and, specifically, cascades involving the interferon-inducible protein 3 (IFITM3) were common between SARS-CoV-2 infection and Alzheimer’s disease." (PMID 38785545, 2024). "This link of IFITM3 with Alzheimer’s disease (AD) pathology, an aging-related neurodegenerative disease, led us to study the expression of IFITM3 and other IFITM family genes and identify the role of IFITM3 in stroke in the aged brain." (PMID 36012150, 2022).